IL1B (interleukin 1 beta)
Diseases named in the same sentence as IL1B in open-access papers (continued):
Sharing a sentence is not in itself a finding about the gene and the disease.
colitis (continued). "The findings from this study demonstrate that PNE improves colon inflammation in acetic acid‐induced colitis by increasing serum glutathione levels while inhibiting nitric oxide production and serum expression of the pro‐inflammatory cytokines, TNF‐α and IL‐1β." (PMID 37249276, 2023). "Oral QT-loaded silk fibroin nanoparticles (QSFN) can produce obvious intestinal anti-inflammatory properties by down regulating proinflammatory cytokines (TNF-α, IL-1β, IL-6, MCP-1, ICAM-1, NLRP3, iNOS) and significantly reducing the DAI score of DSS-induced colitis mice." (PMID 37033644, 2023). "We tested the genetic expression of inflammatory cytokines and found that the LCP diet reduced their expression in colitis, particularly in the P10 group, wherein levels of TNF-α, IL-1β, and IL-6 were diminished 3.0-, 3.2-, and 2.1-fold compared to the M group." (PMID 37761037, 2023). "Also, stimulation of canine MSCs with TNFα elevates TSG-6 and PGE2 resulting in in vivo benefit by regulating colonic inflammatory cytokines such as IL1β, IL6, and IL10, and ameliorating induced colitis in mice." (PMID 37275605, 2023). "Abnormal immune responses in the gut are a feature of colitis, which is characterized by the increase of inflammatory cytokines (TNF-α, IL-1β, IL-6, etc) and decrease of anti-inflammatory cytokines, such as IL-10, and these changes are observed in patients with IBD and DSS-induced colitis mice." (PMID 37297494, 2023). "Others also demonstrate that inhibiting ILK abrogates NLRP3-mediated IL-1β production, that ILK knockdown reduces TNF-α production via NF-κB, and that ILK knockout in intestinal epithelial or myeloid cells reduces DSS-induced colitis in mice." (PMID 36930690, 2023). "Our data show the participation of other cytokines besides IL-6, such as G-CSF, MCP-1, IL1β, and IL10, which are upregulated during DSS-induced colitis in the susceptible AIRmin SS and not in the resistant AIRmin RR mice." (PMID 36792680, 2023). "The IL-1β production levels were remarkably increased in the culture medium of CD11b+CD103- DCs by FimH, whereas FimH treatment did not enhance these levels in CD11b+CD103+ DCs in the mLN of DSS-induced colitis." (PMID 38077339, 2023). "Additionally, after the occurrence of colitis, proinflammatory cytokines, such as TNF-α, IL-6 and IL-1β, are secreted and accumulated in large quantities due to the excessive activation of immune cells." (PMID 36902109, 2023). "Subsequently, we further analyzed the level of inflammatory factors in colon tissue and found that the pro-inflammatory cytokines IL-1β, IL-6, IL-12, IL-17 and TNF-α were increased and the anti-inflammatory cytokine IL-10 was decreased in the colon of DSS-induced colitis." (PMID 37438752, 2023). "We highlight the importance of changes in the microbiota, IL-1β production, and neutrophil accumulation, and propose a possible pathway of microbiota – IL-1β–neutrophil regulation in C. difficile-driven gut inflammation in DSS-induced colitis." (PMID 36951545, 2023). "In order to detect whether paroxetine could regulate PGE2, INF-γ, IL-1β, and IL-10 levels in mice with DSS-induced colitis, ELISA was used to examine the levels of PGE2, INF-γ, IL-1β, and IL-10 in LPMCs." (PMID 37242446, 2023). "According to the results, VK2 restored the colon lengths, improved the colonic histopathology, reduced the levels of proinflammatory cytokines (such as IL-1β, TNF-α, and IL-6), and boosted the level of the immunosuppressive cytokine IL-10 in the colon tissues of the colitis mice." (PMID 36769323, 2023). "Besides, consistent with the in vitro results, pro-inflammatory cytokine levels (including IL-1β and TNF-α) in the colon tissues and blood serum were lower in the PEG-CNPs group than in the colitis group." (PMID 37507801, 2023). "Furthermore, the anti-colitis activity of shionone was also observed with a reduction in inflammation and inflammatory factors such as NLRP3, caspase 1, and IL-1β in the colon." (PMID 38202771, 2023).
colitis (continued). "Our study showed that the newly isolated C4 strain could effectively reduce the expression levels of IL-1β, IL-6, and TNF-α, and upregulate the expression levels of ZO-1 and occludin to alleviate the symptoms in DSS-induced colitis mice." (PMID 37152759, 2023). "Ruminiclostridium-6 could contribute to the release of proinflammatory factors such as IL-6, IL-1β, TNF-α and IL-8 and deteriorate colitis." (PMID 37679821, 2023). "Overall, these results suggest that the excessive production of IL-1β and IL-18 following upregulated activation of inflammatory caspases in the LP could explain the exacerbation of VAD DSS-induced colitis." (PMID 37240022, 2023). "Finally, the mouse model of colitis was established and SOD, MDA, TNF-α, IL-1β, IL-6 and P38 as well as ERK were detected from mice." (PMID 38024351, 2023). "Moreover, DCA administration aggravated TNBS-induced colitis by promoting Gasdermin D (GSDMD)-mediated pyroptosis and IL-1beta (IL-1β) production in macrophages." (PMID 37131223, 2023). "Esculin was found to significantly alleviate the symptoms of colitis and suppress the expression of inflammatory factors including inducible nitric oxide synthase (iNOS), tumor necrosis factor-α (TNF-α), and interleukin-1β (IL-1β) in vivo and in vitro." (PMID 37800835, 2023). "Exogenous administration of IL-1β reduces the expression of colonic Th2 cytokines IL-4 and IL-13 and improves colitis, while exogenous IL-18 also reduces the severity of colitis but does not affect the expression of Th2 cytokines." (PMID 37370025, 2023). "Furthermore, PELNs demonstrated the ability to suppress the expression of pro-inflammatory cytokines (IL-6, IL-12, IL-1β, and TNF-α) and MPO, and increase the levels of the anti-inflammatory cytokine IL-10, thereby alleviating DSS-induced colitis in mice." (PMID 37653406, 2023). "Other studies report that resveratrol reduces inflammation in patients with UC to improve their quality of life and disease clinical colitis activity, and in animal models of IBD, where there are reduced pro-inflammatory markers (TNF-α, IFN-γ, IL-1β, IL-6, and IL-4) and DAI." (PMID 37660064, 2023). "To examine whether the protective effects of colitis were limited to a specific model of CFA-induced arthritis, we used the mBSA/IL-1β-induced arthritis model." (PMID 36793721, 2023). "In addition, live probiotic L. johnsonii suppressed TNF and IL-1β expression and stimulated anti-inflammatory cytokine (IL-10) expression in the colon of trinitrobenzenesulfonic acid (TNBS)-induced colitis mice." (PMID 36986118, 2023). "Thus, a significant increase in mRNA of TNF, IL-6, IL-1β, and ICAM-1 genes in the proximal colon in mice with DSS-induced colitis compared with control mice." (PMID 36359839, 2022). "Also, in other studies, serum TNF-α level was decreased in obese mice fed a high-fat diet supplemented with RB compared to obese mice, and γ-oryzanol significantly reduced the up-regulated expression of IL-1β, IL-6, TNF-α, and COX-2 mRNA in mice with colitis." (PMID 34636986, 2022). "Exacerbated colitis, aggravated changes in colon length, MPO, TNF-α and IL-1β in gut tissue." (PMID 35893902, 2022). "Indeed, single-cell RNA-Seq of colon tissues from patients who developed immunotherapy-induced colitis not only showed increased proinflammatory monocytes, but also showed increased expression of proinflammatory cytokines TNF-α and IL-1β." (PMID 36173679, 2022). "On the other hand, the colonic expression levels of IL-1β and IL-6, which were known to be major macrophage cytokines, were significantly higher in mPGES-1−/− mice than in WT mice under either the GK1.5 or LTF2 treatment during DSS-induced colitis." (PMID 34983695, 2022). "The relationship between variables related to colitis and the core microbiota communities in the PHE group demonstrated that the abundance of Akkermansia was negatively related to the expression of PGE2, IL-6, and IL-1β." (PMID 36569313, 2022).
colitis (continued). "Furthermore, the levels of inflammatory mediators and cytokines, including TNF-α, IL-1β, and IL-6, were significantly lower in the BCP group than those in the untreated DSS-induced colitis group." (PMID 36431883, 2022). "During colitis, TNF-α and IL-1β are secreted from monocytes and leukocytes." (PMID 36225573, 2022). "Also, G. lucidum ethanol extract administration decreased the expression of inflammatory mediators IL-1β, IL-6, IL-17, and TNF-α in DSS-induced colitis." (PMID 36553765, 2022). "Experimentally, treatment with yeast worsened the DAI in DSS colitis and exacerbated ASCA levels, in addition promoted serum and colonic tissue pro-inflammatory cytokine secretion (TNF- α, IL-1β and IL-6) and stimulated the expression of NF-κB in colonic tissue." (PMID 36384756, 2022). "Indeed, the release of IL-1β is driven by the activated NOD-like receptor family pyrin domain containing 3 (NLRP3) inflammasome, which is harmful in colitis." (PMID 36145301, 2022). "Combined treatment reduced colitis inflammation by neutralizing TNF-α and blocking TNFR1, down-regulating colonic expression of TNF-α by disrupting positive feedback and the gene expression of IL-1β and IL-8 in peritoneal macrophages." (PMID 35939430, 2022). "AL-1 ameliorated DSS-induced colitis in mice by inhibiting NF-κB and MAPK signaling pathways, reduced iNOS, COX-2, NO and PGE2 in cultured macrophages, significantly reduced production of IL-1β, IL-6, TNF-α, PGE2 and IFN-γ, and increased secretion of IL-10." (PMID 36238575, 2022). "We show that BBR suppresses the activation of macrophages and granulocytes in colitis mouse models, accompanied by decreases in the production of inflammatory cytokines including IL1β, TNFα, and IL6, yet, T cells are not significantly affected." (PMID 36528592, 2022). "The elevated levels of IL-1α, IL-1β, IL-3, IL-6, IL-9, IL-12 (P40), IL-12 (P70), IL-17, GM-CSF, and G-CSF in response to DSS treatment in the current study, supports the strong involvement of macrophage activation in the DSS induced colitis model." (PMID 36365201, 2022). "Not surprisingly, C3G inhibited NF-κB phosphorylation, reduced mRNA expression of pro-inflammatory cytokines including IL-1β, IL-6, IL-8, COX-2, and TNF-α, and protein levels of apoptosis related genes in DSS-induced colitis mice, providing new ideas for using C3G as adjuvant agent for treating UC." (PMID 35805952, 2022). "Acetic acid-induced colitis in rats showed a significant increment (P < 0.0001) in IL-1β and TNF-α levels compared with the negative control group." (PMID 35428860, 2022). "Furthermore, in mice with DSS-induced colitis, FXR activation decreases local IL1β and increases systemic IL10 expression." (PMID 35807844, 2022). "In conclusion, our results revealed that oral administration of BCP in DSS-induced ulcerative colitis mice improved colitis by reducing MPO activity, IL-1β, IL-6, and TNF-α concentrations, as well as the abundance of bacteria that cause intestinal immune imbalance." (PMID 36431883, 2022). "The sequel of events triggered by TLR-4 activation, including NF-kB and NLRP3 activation, and the release of IL-1β, IL-6, and TNF-α, are considered the most involved in persistent intestinal inflammation triggering and maintenance during colitis, and HIV-1 Tat-induced diarrhea." (PMID 36009057, 2022). "All the rats exposed to 3% DSS for 7 days developed acute colitis, as evidenced by the increase in the DAI, the shortening in the colon length, and the increase in the mRNA relative abundance of the pro-inflammatory cytokines IL-1β, IL-6, and TNF-α." (PMID 35628158, 2022). "The monitoring of NLRP3 inflammasome protein levels in the inflamed colon tissue of Kunming mice (colitis model), by Western blot analysis, after sinapic acid treatment for 7 days, have shown a reduction in the amounts of NLRP3, ASC, IL-1β, and caspase-1 proteins." (PMID 35276849, 2022).
colitis (continued). "In our study, T. halophilus suppresses serum IL-1β and TNFα levels in DSS-induced colitis mice." (PMID 35741032, 2022). "Moreover, B. vulgatus Bv46 treatment reduced the expression of colonic TNF-α, IL-6 and IL-1β in the DSS-induced mouse colitis in vivo and the TNF-α, IL-6 and IL-1β release in the supernatants of LPS-activated macrophage cells in vitro." (PMID 36531989, 2022). "In DSS-induced colitis, mice that were fed experimental diets containing AST (100–200 ppm) exhibited lowered gene expressions of several inflammatory markers including TNF-α, IL-1β, IL-6, COX-2, and iNOS and inhibited NF-κB expression in the colon." (PMID 36555112, 2022). "In the present study, colonic expressions of IL-1β and IL-6, major macrophage-related proinflammatory cytokines relevant to IBD, were still exacerbated in mPGES-1−/− mice under the CD4+ T cell depletion during colitis." (PMID 34983695, 2022). "Likewise, in a murine colitis model, treatment with a P2X7R antagonist, A438079, reduced the production of inflammatory cytokines, TNF and IL-1β, in colon tissue." (PMID 35492615, 2022). "Peroral treatment with L. reuteri improved colitis severity clinically and morphologically and reduced the colonic levels of Tumor necrosis factor-α (TNF-α) (Tnf), Interleukin 1-β (Il1β), and nterferon-γ (Ifng), the crucial pro-inflammatory cytokines in colitis onset." (PMID 35320932, 2022). "In addition, in the colitis model, elevated levels of pro-inflammatory cytokines (TNF-α, IL-1β and IL-6) were found to enhance the inflammatory cascade and cause intestinal tissue damage in UC patients." (PMID 36555167, 2022). "Ursolic acid inhibits the activation of NF-κB and MAPK signaling pathways in IECs and macrophages, reduces TNF-α, IL-1β, COX-2, and iNOS in TNBS-induced colitis in mice as well as in LPS-stimulated inflammatory cells expression levels and attenuate the inflammatory response." (PMID 35873579, 2022). "Previous studies focused on the expression of IL-1β and TNFα as promising proinflammatory cytokines in the absence of mPGES-1 during colitis." (PMID 34983695, 2022). "However, we found that IL-1β is elevated in the acute DSS model of colitis in mice, as it is in the hippocampus of mice with chronic DSS colitis." (PMID 35379260, 2022). "In acetic acid-induced colitis of Sprague–Dawley rats, nicotine (1 mg/kg, i.p.)reduced the extent of colonic lesions, colonic malondialdehyde (MDA) level, MPO activity, NF-κB expression, and serum IL-1β level." (PMID 35251010, 2022). "Evelyn Saba and colleagues found that ginsenoside Rg3 (20 mg/kg) could decrease the expression of pro-inflammatory mediators and cytokines including NO, IL-1β, IL-5, IL-13, and TNF-α, and levels of NLRP3 inflammasome in DSS-induced colitis mice." (PMID 36160392, 2022). "Moreover, GLPN with lower Mw fraction exhibited anti-inflammatory activity through preventing colon length shortening and inhibiting the production of pro-inflammatory cytokines including TNF-α, IL-1β, and IL-6 in DSS-induced colitis mice." (PMID 36245525, 2022). "We also confirmed that during colitis, a lack of mPGES-1 facilities increased expression levels of IL-1β, in addition to IL-6." (PMID 34983695, 2022). "A study reported that glycyrrhetic acid (10, 50 mg/kg) could decrease the levels of IL-6, IL-1β, and TNF-α, and suppress the expression of COX-2, NF-κB, and PGE2 protein for treating the DSS-induced colitis mice." (PMID 36160392, 2022). "However, in this study, these two cytokines were not significantly changed, which differed from a previous report that L. acidophilus can down-regulate IL-1β and TNF-α to improve colitis." (PMID 36499169, 2022). "Similarly, less pronounced activation of the NF-κβ signaling pathway and decreased expression of inflammatory cytokines, including IL-1β, IL-6, MCP1, and CCL3 were observed in the colon of KO to WT compared to WT chimera mice with DSS colitis." (PMID 35743072, 2022).
colitis (continued). "In addition, ZBE inhibited TNF-α, IL-1β, and IL-12 by regulating the TLR4-and TLR4-related pathways in mice and LPS-induced cellular inflammation in DSS-induced experimental colitis." (PMID 36081930, 2022). "The aggravated colitis in mice lacking IL-38 was accompanied by a greater increase in the pro-inflammatory cytokines IL-1α and IL-1β in the colon compared to WT mice." (PMID 35693797, 2022). "Cyanidin-3-glucoside and cyanidin were reported to downregulate the proinflammatory mediator nitric oxide, as well as proinflammatory cytokines TNF-α, IL-1β, IL-6, and IFN-γ in 2,4,6-trinitrobenzenesulfonic acid (TNBS)-induced colitis mice and lipopolysaccharide (LPS)-stimulated Caco-2 cells." (PMID 35204188, 2022). "Interestingly, serum levels of Il-1β, Tnf, and Il-6 in DSS-induced colitis are further increased by transient hypoxia." (PMID 36232412, 2022). "It was shown that Sinomenine significantly improved the inflammatory response of intestinal mucosa in colitis, inhibited the secretion of IL-1β and TNF-α, and improved the severity of colitis in mice by downregulating the level of miRNA-155 and other related inflammatory cytokines." (PMID 35873579, 2022). "Moreover, the acute colitis produced a strong induction of mRNA expression levels of TNF-α, IL-1β, IL-6 and CXCL10, ranging from 233.5 ± 24.0% for IL6 to 663.5 ± 195.8% for TNF-α, in WTDSS mice compared to control group (p <0.05)." (PMID 34483912, 2021). "FCPS treatment could ameliorate colitis symptoms by restoring the expression of light junction protein claudin-1 and down-regulating the level of TNF-α and IL-1β in the DSS-induced colitis mice." (PMID 34199820, 2021). "The rodents with colitis induced by the administration of trinitrobenzenesulfonic (TNBS) acid exhibited intensification of the inflammatory changes and increased synthesis of IL-1β and TNF-α, following having been infected with fungi of the genus Candida." (PMID 34578152, 2021). "As ILC3s were the major GM-CSF-producing cell type in the colon during colitis, sorted RORγt+ ILC3s or ILC3-conditioned media were co-cultured with BMDM, resulting in an enhancement of the IL-1β, MHC-II expression in BMDM and suppression of IL-10 (characteristics of M1 macrophage)." (PMID 34659248, 2021). "In addition, we found that curcumin promoted the release of the anti-inflammatory cytokines IL-10 and IL-33 in colitis mice and inhibited the secretion of the proinflammatory cytokines CCL-2, IL-1β, and IL-6." (PMID 34567209, 2021). "The mRNA expression levels of TNFα, IL-1β, and IL-6 were increased by nearly 12-, 18-, and 16-fold, respectively, and the secretion levels of TNFα, IL-1β, and IL-6 were elevated by approximately 2-, 10-, and 3-fold, respectively, in DSS-induced colitis." (PMID 34880751, 2021). "Moreover, RX821002 reduced the production of inflammatory cytokines in colonic homogenates, such as TNFα and IL-1β, when compared with DSS-induced colitis." (PMID 34884737, 2021). "Recent studies have illustrated that excessive NLRP3 inflammasome–induced IL-1β aggravates colitis, and the absence of NLRP3 inflammasome components has a protective role in the dextran sodium sulfate (DSS)-induced colitis model." (PMID 34322027, 2021). "Beta-sitosterol was found to markedly reduce weight loss, colonic length shortening, and microscopic changes in DSS-induced colitis and to reduce TNF-α, IL-6, and IL-1β levels in the intestinal tissues of experimental colitis mice in a concentration-dependent manner." (PMID 34149863, 2021). "As well, decreased levels of IL-1β, IL-6, IL-8, and TNF-α in the plasma, and decreased levels of IL-6 and TNF-α, and increased level of MPO in the colon were shown in mice with colitis treated by EGCG-FMT compared with other three groups." (PMID 34493333, 2021). "Collectively, our data indicate that exogenous IL-1β protects Gsdmd-/- mice from acute colitis, and thus the decreased IL-1β is not the major reason for the protection against colitis in Gsdmd-deficient mice." (PMID 34721422, 2021).